MUC1 (mucin 1, cell surface associated)
Diseases named in the same sentence as MUC1 in open-access papers (continued):
Sharing a sentence is not in itself a finding about the gene and the disease.
metastatic carcinoma (14 papers, 2009 to 2025). A carcinoma which has spread from the original site of growth to another anatomic site. "Considering that MUC1 exerts a prominent role in PDAC progression, and its overexpression correlates with metastatic cancer and poor prognosis, several studies were conducted to elucidate the MUC1 involvement in regulation of anoikis." (PMID 40001578, 2025). "In a model of metastatic cancer, transgenic mice that constitutively express MUC1 were also injected with B16‐MUC1 cells." (PMID 31989033, 2020). "Seven patients in the group with low MUC1 expression had metastatic carcinoma in the axillary lymph nodes, whereas only 1 patient had a positive lymph node in the high MUC1 group (p = 0.008)." (PMID 27846863, 2016). "According to the subject data, a higher expression of MUC1 is observed in more invasive metastatic cancer." (PMID 22726603, 2012). "In line with our previous colony formation experiments, we found an increase in proliferating metastatic cancer cells (MUC1+Ki67+) in gemcitabine treated PCLS cultures supplemented with recombinant Gas6 compared with gemcitabine treated PCLS cultures lacking recombinant Gas6." (PMID 35022267, 2022). "The study also provided potential strategies to treat metastatic cancer, as both DMBT1 targeting with a neutralizing antibody and MUC1 inhibition by GO203 effectively suppresses NET formation and liver metastasis." (PMID 40796724, 2025). "Internalizing SHALs targeting under-glycosylated MUC1, the androgen receptor and other tumor specific cell surface proteins that residualize the radioisotopes they carry could also be developed as small molecule therapeutics for a wide variety of other types of metastatic cancer." (PMID 19383174, 2009). "MUC1 has an influential role in variety of cell proliferation pathways, including vascular proliferation though VEGF pathways in mucosal tissues, and metastatic carcinoma progression through JAK/STAT and phosphorylation signaling pathway interactions, leading to endothelial mesenchymal transition." (PMID 38036513, 2023).
Sepsis (14 papers, 2014 to 2024). Sepsis is defined as life-threatening organ dysfunction caused by a dysregulated host response to infection. "MUC1/KL-6 mainly exerts anti-inflammatory effects through the intracellular segment during the occurrence of acute lung injury caused by sepsis." (PMID 36447946, 2022). "Besides, inhibiting MUC1 reversed the alleviating effect of vitamin E on ALI caused by sepsis, increased the aggregation of inflammatory cells in lung tissues, and aggravated alveolar injury and edema." (PMID 35910848, 2022). "Western blotting and immunofluorescence revealed that JHD restored the expression of ZO-1 and Muc-1 in colon tissues in sepsis mice." (PMID 37081964, 2023). "Meanwhile, we also found that the expression level of MUC1 (KL-6) in the plasma of sepsis patients complicated with ARDS was significantly increased and had a good predictive value for early sepsis patients complicated with ARDS." (PMID 35910848, 2022). "Of note, Muc1 is increased considerably after infection, a finding that is in agreement with our observation that Muc1 and Muc2 genes were upregulated after induction of experimental sepsis." (PMID 32041659, 2020). "Our research group has been focused on the role of MUC1 in sepsis-induced ALI/ARDS." (PMID 35910848, 2022). "Through further exploration, we found that MUC1 had a sensitization effect on vitamin E. MUC1 could promote the protective effect of vitamin E on lungs of sepsis and reduce the levels of inflammatory factors in sera and BALF." (PMID 35910848, 2022). "Previous studies have shown that MUC1 could relieve ALI in sepsis and predict whether sepsis patients would develop into ARDS." (PMID 35910848, 2022). "Our study was the first to explore the changes of iron metabolism indicators in ALI/ARDS of sepsis, clarify the important role of ferroptosis in ALI/ARDS induced by sepsis, and reveal the effects and specific mechanisms of MUC1 in regulating ferroptosis, as well as the sensitization on vitamin E." (PMID 35910848, 2022). "However, whether MUC1 plays a role in the ferroptosis of ALI/ARDS in sepsis remains obscure, and the specific mechanism needs to be illustrated." (PMID 35910848, 2022). "Besides, MUC1 might be a biomarker for predicting whether patients with early sepsis would develop into ARDS, which had important potential application value." (PMID 35910848, 2022). "However, the mechanism of MUC1 in alleviating lung injury of sepsis was still unclear." (PMID 35910848, 2022). "However, the role of MUC1 in the ferroptosis of sepsis-induced ALI/ARDS remains unclear." (PMID 35910848, 2022). "Currently, the role and mechanism of vitamin E in ferroptosis from ALI/ARDS in sepsis has not been elucidated, and there is a lack of relevant studies on the interaction between MUC1 and vitamin E." (PMID 35910848, 2022). "This has already been acknowledged for MUC1, where increased levels of this mucin have also been described in patients with ARDS and sepsis-induced acute lung injury but remains unclear for the other mucins investigated in this study." (PMID 34448730, 2021).
chordoma (13 papers, 2012 to 2025). Chordomas are rare malignant tumors arising from embryonic remnants of the notochord in axial skeleton. "Chordomas were classically identified on the basis of their histological features and their immunoreactivity for S-100 and markers such as epithelial membrane antigen (MUC1) and cytokeratins." (PMID 23662285, 2013).
lymphoma (13 papers, 1991 to 2025). A malignant (clonal) proliferation of B- lymphocytes or T- lymphocytes which involves the lymph nodes, bone marrow and/or extranodal sites. "Two weeks after the last dose of vaccine, mice were challenged subcutaneously with RMA-MUC1 cells, a lymphoma T cell line that expresses MUC1." (PMID 37372999, 2023). "Our basic understanding of the functional and mechanistic involvement of MUC1-Cter in tumorigenesis resulted in development of peptide inhibitors such as GO-203-2C, which is under phase-I clinical trial (NCT01279603) against patients with advanced solid tumors and lymphoma." (PMID 25691062, 2015).
mesothelioma (13 papers, 2008 to 2025). A usually malignant and aggressive neoplasm of the mesothelium which is often associated with exposure to asbestos. "Next, we performed coculture with N5.14 cells and Meso13, a mesothelioma cell line presenting the specific antigen MUC1." (PMID 35967413, 2022). "First, we investigated in the same way the impact of DCMU on another cancer-specific CD8+ T-cell clone, this time specific for the mesothelioma antigen MUC1 (N5.14)." (PMID 35967413, 2022). "Seven of 9 mesothelioma samples expressed MUC1-secreted mRNA isoform in addition to the archetypal MUC1/transmembrane form." (PMID 18454162, 2008). "MUC1 mRNA expression was significantly higher in mesothelioma samples than in benign mesothelial cells." (PMID 18454162, 2008). "To this end, we examined IFN-γ expression and the cytotoxic response of a CD8+ cytotoxic T-lymphocyte (CTL) clone that specifically recognizes the HLA-A2/MUC1 peptide complex after contact with a luciferase-expressing mesothelioma cell line expressing this complex." (PMID 35012660, 2022). "We suggest that the specific hypoglycosylated form of the full length tandem repeat containing MUC1 protein product is a useful target for mesothelioma diagnosis, but possibly the expression of novel MUC1 epitopes may represent a potential therapeutic target." (PMID 18454162, 2008). "Our findings suggest that the role of MUC1-directed therapy in mesothelioma should be investigated." (PMID 18454162, 2008). "Thus, as in other cancers, alterations in MUC1 biology occur in mesothelioma and these results suggest that specific MUC1 characteristics may be useful for mesothelioma diagnosis and should also be investigated as a potential therapeutic target." (PMID 18454162, 2008). "Herein, we studied the cell surface and soluble expression of the MUC1/EMA glycoprotein, and determined the mRNA and genomic expression profiles in mesothelioma." (PMID 18454162, 2008). "CA15.3 (soluble MUC1) levels were significantly higher in the serum of mesothelioma patients than in healthy controls but were not significantly different to levels in patients with benign asbestos-related disease." (PMID 18454162, 2008). "While the secreted splice form was detected in malignant mesothelial cells, it is of particular note that the expression of the full length, VNTR containing MUC1 gene product was 32-fold higher in mesothelioma than in normal cell preparations." (PMID 18454162, 2008). "As the majority of epithelioid mesotheliomas demonstrate strong MUC1/epithelial membrane antigen (EMA) positivity by immunohistochemistry similar anti-MUC1 therapeutic strategies may have potential in mesothelioma." (PMID 18454162, 2008). "The relative expression of the archetypal, full-length, transmembrane MUC1 isoform, MUC1-TM, normalised to GAPDH, was significantly greater in the cells from pleural effusion (P<0.0001) and surgically-excised tumour (P=0.001) mesothelioma samples than that in normal mesothelial cells." (PMID 18454162, 2008).
glioma (12 papers, 2017 to 2024). A benign or malignant brain and spinal cord tumor that arises from glial cells (astrocytes, oligodendrocytes, ependymal cells). "Specific mucins that have now been implicated in glioma include MUC1, MUC4, MUC15, MUC16, MUC17, MUC18 and MUC21." (PMID 39767713, 2024). "For instance, in trial NCT03383978, NK-92 cells modified to express anti-MUC1 CARs are being administered via intracranial injection to target MUC1-positive gliomas." (PMID 38732975, 2024). "Based on CRISPR-Cas9 screening, it was found that MUC1 is essential for EGFRvIII glioma cell survival and TMZ resistance as it was upregulated in EGFRvIII-positive cells." (PMID 39767713, 2024). "Transcriptome analysis of naive and shMUC1 glioma cells indicated that MUC1 primarily regulates EMT and telomere-related pathways." (PMID 39201386, 2024). "Taken together, these results suggested the MUC1 promotes glioma tumorigenesis through cell cycle regulation, telomere maintenance mechanism and EMT." (PMID 33106534, 2020). "Among the differentially expressed genes identified, MUC1 was one of the significantly upregulated genes (p-value < 0.05, log2FC ≥ 2) in glioma tissue." (PMID 33106534, 2020). "The CARs in current studies are led by scFv against five antigens (HER-2, EGFRvIII, MUC-1, IL13Rα2, and EphA2), specific for antigens expressed on glioma cells and/or other solid tumors." (PMID 28993773, 2017). "In non-glioma settings, MUC1-C has been associated with metabolic reprogramming in esophageal squamous cell carcinoma (ESCC) via the inhibition of the AKT pathway, making MUC-1 a potential target for treating ESCC." (PMID 39767713, 2024). "The expression level of MUC1 was analyzed in human glioma and paired normal brain tissues." (PMID 33106534, 2020). "Using GBM and lower grade glioma (LGG) data from TCGA (The Cancer Genome Atlas) and normal brain data from GTEx (Genotype-Tissue Expression), we could confirm that the MUC1 was overexpressed in glioma tissue compared with normal brain." (PMID 33106534, 2020). "However, the role of MUC1 in glioma cells has been rarely studied." (PMID 33106534, 2020). "Based on the current literature, expression profiles, and biological properties, MUC1, MUC4, MUC16, and MUC18 are of interest as precision biomarkers in glioma." (PMID 39767713, 2024). "RNA sequencing of paired normal brain and tumor tissue from 30 patients revealed that MUC1 was significantly upregulated in glioma, regardless of WHO grade." (PMID 39201386, 2024). "The upregulation of MUC1 was a universal phenomenon in gliomas regardless of their WHO grades, although only high-grade gliomas including GBM showed statistical significances." (PMID 33106534, 2020).
viral infections (12 papers, 2009 to 2025). "MUC1 appeared in mammals to protect respiratory tract epithelia and other barrier tissues from loss of homeostasis by viral infections The A3 enzymes evolved in mammals to protect against replication of ERVs." (PMID 40781226, 2025). "MUC1/Muc1 (humans/mice) has been implicated in various aspects of both bacterial and viral infections." (PMID 35699372, 2022). "Our estimation results provide evidence that MUC1 reduces the susceptibility of epithelial cells to viral infection." (PMID 34066999, 2021). "The MUC1 gene evolved in mammals to defend barrier tissues from viral infections and other biotic insults." (PMID 40764753, 2025). "The MUC1 gene evolved in mammals to provide barrier tissues, such as respiratory epithelia, with protection from viral infections and abiotic environmental insults." (PMID 40781226, 2025). "MUC1 also has been shown to play a critical role in several other virus infections, including those by respiratory syncytial virus, adenovirus, influenza virus, and human immunodeficiency virus." (PMID 35479093, 2022). "Future studies are needed to elucidate the role of NEUs, if any, in regulating the MUC1-dependent responses to virus infections." (PMID 35479093, 2022). "Biologically, the median estimate for ε1 indicates that the presence of MUC1 reduces the rate of virus infection to epithelial cells by 44% (for the TIV model) or 42% (for the IR model)." (PMID 34066999, 2021). "The decreased R0 suggests that MUC1 expression contributes to limit and delay viral infection, and more importantly, to prevent viral dissemination within the host." (PMID 34066999, 2021). "Our data suggest that knockout of Muc-1 inhibits expression and activation of NF-κB during viral infection, whereas wildtype mice exhibit robust NF-κB mediated proinflammatory signaling that results in pancreatitis and consequent inflammatory responses." (PMID 31337812, 2019). "Among the cell surface mucins, MUC1 is the most studied cell-surface mucin and its anti-inflammatory role initiated by bacterial and viral infection has been well established." (PMID 31307416, 2019). "Despite anti-inflammatory or antiviral functions being revealed for certain cell-surface mucins such as MUC1, the roles of other mucins are still poorly understood, especially in viral infections." (PMID 31307416, 2019). "The MUC1 gene evolved in mammals to protect barrier tissues from viral infections." (PMID 40764753, 2025). "The MUC1 gene appeared in mammals to protect barrier tissues from viral infections." (PMID 40781226, 2025). "MUC1 is induced in response to viral infections, which may be related to the activation of cytosolic nucleotide receptors by the presence of viral DNA and contribute to increased levels of MUC1-C expression in MCCP cells." (PMID 35688945, 2022). "In conclusion, these investigations reveal that a variety of human and animal virus infections are impacted by the expression and activity of NEU1, NEU2, NEU3, and MUC1." (PMID 35479093, 2022). "While the expression of MUC1 has little impact on the cumulative viral load (AUCV), it delays viral infection by reducing the basic reproduction number of viral replication and delaying viral load peak time." (PMID 34066999, 2021). "In addition, MUC1 is the first cell-surface mucin with anti-influenza function, and it was reported that MUC1 and MUC15 in the milk-fat globule membrane milk can limit bacterial and viral infections of the gastrointestinal tract." (PMID 31307416, 2019). "Here, we explored potential functions of Muc-1 in inflammation that accompanies CVB3-induced pancreatitis, and discovered that mice lacking Muc-1 showed a dramatically attenuated inflammatory and tissue remodeling reaction to virus infection." (PMID 31337812, 2019). "However, despite the many studies on MUC1, the role of other cell-surface mucins in the airway during viral infection has not been well illustrated and demonstrated." (PMID 31307416, 2019).
viral infections (continued). "Taken together, these findings support the hypothesis that Muc-1 influences local NF-κB-mediated proinflammatory signaling, which leads to de novo expression of ICAM-1 in the vicinity of viral infection, which in turn enhances macrophage infiltration into the infected and inflamed areas." (PMID 31337812, 2019).
colon adenocarcinoma (11 papers, 2004 to 2018). "Indeed, a recent study revealed the role of MUC5AC, MUC1 and proteoglycans in the inhibition of E-cadherin function associated with invasiveness of HT-29 colon adenocarcinoma cell variants." (PMID 14760390, 2004). "In vitro studies performed in the colon adenocarcinoma cell line LS174T showed upregulation of MUC1 by probiotic strains, including EcN." (PMID 27242727, 2016). "We could also detect the gastric mucins MUC5AC and MUC1 in these cell lines, which is explained by that they are established from human colon adenocarcinomas, and cancer is known to induce changes in type of mucin production." (PMID 23869232, 2013). "Regarding immunohistochemistry, adenocarcinoma of the urinary bladder expresses CEA, CDX-2, MUC-1, MUC-2 and MUC-3, same as colonic adenocarcinoma." (PMID 20205820, 2010).
gastritis (11 papers, 2009 to 2025). Inflammation of the stomach. "It has been reported that MUC1 plays a crucial role in Helicobacter pylori-associated gastritis via acting as a protective physical barrier against pathogens." (PMID 41154387, 2025). "They showed that smaller VNTR genotypes of the MUC1 gene increase susceptibility to intestinal metaplasia in Colombian patients with gastritis." (PMID 38463926, 2024). "Human population studies have found associations between MUC1 allele polymorphisms and susceptibility to the development of gastric adenocarcinoma and H. pylori-associated gastritis." (PMID 19816567, 2009). "Moreover, immunohistochemical analysis of 95 patients with gastritis in Northern Europe showed relation between susceptibility to gastritis and the length of MUC1 gene functional allele." (PMID 38463926, 2024). "Indeed, it was reported on Caucasians that those having the S allele of MUC1, which is linked to the A allele of rs4072037, were more susceptible to HP gastritis than the people with the L allele." (PMID 24810688, 2014). "Previous studies have revealed that MUC1 can inhibit NLRP3 inflammasome activation in Helicobacter pylori gastritis and bacterial infection, but they mainly studied NLRP3 inflammasome as an inflammatory mediator." (PMID 37880668, 2023). "Normal MUC1 blocks adhesion of H. pylori to the gastric mucosa, thus preventing H. pylori colonization and gastritis." (PMID 32701958, 2020). "In fact, MUC1 expression in macrophages limits gastritis through regulation of the NLRP3 inflammasome." (PMID 32230726, 2020). "Regulation of NLRP3 inflammatory activity by MUC1 is critical for prevention of severe gastritis." (PMID 38463926, 2024). "In addition, it is not mentioned whether the cancer-free hospital-based controls were gastritis patients, which limits our analyses on the role of MUC1 rs4072037 in gastric carcinogenesis when compared with the population-based healthy controls." (PMID 25332893, 2014). "The non-neoplastic genotype of gastric cells relies, at least partially, on the expression of miR-22 and mucin 1 (MUC1), two players that prevent H. pylori-induced gastritis and gastric carcinogenesis by inhibiting NLRP3 activation." (PMID 37891577, 2023). "In one study, mice lacking Muc1 were colonized by five-fold more HP within one day of infection, and developed an atrophic gastritis marked by loss of parietal cells, although wild-type mice developed only a mild gastritis, when infected for two months with HP." (PMID 24810688, 2014). "Furthermore, the membrane bound mucin MUC1 can act as a releasable decoy hindering prolonged adherence to epithelial cells in vitro, and mice lacking this mucin develop more severe gastritis." (PMID 29638186, 2018).